SNORD116-12 (small nucleolar RNA, C/D box 116-12)
Synonyms: HBII-85-12
Gene: Small nucleolar RNA gene on chromosome 15 (25,077,051 to 25,077,142, forward strand). Ensembl gene ENSG00000207197.
Gene Ontology:
Biological process: RNA processing
Cellular component: nucleolus
Homologues: Orthologues: chimpanzee SNORD116 (99% identical), macaque SNORD116 (88% identical), guinea pig SNORD116 (86% identical), guinea pig SNORD116 (84% identical). Paralogues in human: SNORD116-17 (93% identical), SNORD116-19 (93% identical), SNORD116-14 (92% identical), SNORD116-15 (92% identical), SNORD116-18 (92% identical), SNORD116-20 (92% identical), SNORD116-21 (92% identical), SNORD116-22 (92% identical), SNORD116-16 (90% identical), SNORD116-24 (89% identical), SNORD116-13 (87% identical), SNORD116-23 (87% identical), and 20 more.